CHD7 (chromodomain helicase DNA binding protein 7)
Diseases named in the same sentence as CHD7 in open-access papers (continued):
Sharing a sentence is not in itself a finding about the gene and the disease.
CHARGE syndrome (continued). "For CHD7 variants, the RSV of P or LP is more commonly associated with CHARGE syndrome." (PMID 36245975, 2022). "Our analyses showed 55 mutations in CRC which are dominant of missense mutations, and 53 mutations in CHARGE syndrome which are dominant of truncating mutations, and there was no overlapped site, indicating that the mutations in CHD7 that drive CRC and CHARGE syndrome are totally different." (PMID 35789070, 2022). "Variable expressivity has been observed in patients with positive CHD7 variants, where patients did not meet the diagnostic criteria for CHARGE syndrome." (PMID 36011280, 2022). "Widely observed in clinical work, the alteration of CHD7 expression levels in specific cell lineages leads to severe malfunction or diseases, e.g., CHARGE syndrome, Kallmann syndrome, autism spectrum disorder, developmental disorders of multiple organ systems, and tumorigenesis." (PMID 35418650, 2022). "In summary, we generated two chd7 mutant fish lines as the CHARGE syndrome disease model." (PMID 36568983, 2022). "Although the CHARGE syndrome has been reported as an autosomal dominant condition that is caused by the variants in the CHD7, no de novo rare variants were identified in CHD7 or any other genes in this study." (PMID 33640901, 2021). "Like CHARGE syndrome patients, vestibular ganglia are small in Chd7 mutant mice." (PMID 34589045, 2021). "Using animal models, it has been shown that modulation of the expression of RA signaling during embryogenesis leads to developmental defects similar to those in CHARGE syndrome, suggesting critical cooperative roles for RA and CHD7 in a common pathway to regulate inner ear development." (PMID 34639189, 2021). "Identifying whether specific subtypes undergo neurodegeneration following Chd7 deletion and gaining insights into the disruption of tonotopy may guide improvements in cochlear implants for CHARGE syndrome patients." (PMID 34732824, 2021). "This may be an evidence for the hypothesis that CHD7 variants in humans can lead to a continuous phenotype spectrum, and CHH is just a milder manifestation than CHARGE syndrome." (PMID 35047002, 2021). "Pathogenic variants of CHD7 exist in about 10% of CHH patients, and they are also the major pathogenic cause (detection rate is more than 90%) for another autosomal dominant disease, CHARGE syndrome (OMIM, 214800)." (PMID 35047002, 2021). "Unlike CHD8 and WHSC1, CHD7 has been previously implicated in neurocristopathy (CHARGE syndrome) and the motility of NCCs." (PMID 33554859, 2021). "It has been postulated that a functional interaction between CHD7, TBX1 and RA signaling could explain the phenotypic overlap in DGS due to CHARGE syndrome, 22q11.2del, TBX1 deficiency, and RA embryopathy." (PMID 33257998, 2021). "Here, we identify the Chromodomain Helicase DNA Binding Protein 7 (CHD7), which is frequently mutated in CHARGE syndrome, as an integral component of the non-homologous end-joining (NHEJ) DSB repair pathway." (PMID 33188175, 2020). "CHD7 has been established as the major disease gene for CHARGE syndrome (OMIM #214800)." (PMID 32502225, 2020). "Furthermore, the effect of FIRΔexon2 on FGF8 mRNA splicing was examined as an indicator of neural development due to impaired CHD7 revealed in CHARGE syndrome." (PMID 32071290, 2020). "Two recent studies showed that patients harboring missense mutations in CHD7 predominantly suffer KS, whereas truncating mutations (nonsense, frameshift, and splicing mutations) mostly result in traditional CHARGE syndrome." (PMID 31355196, 2019). "The CHD7 gene is the only known gene responsible for 90%~ 95% of typical CHARGE syndrome." (PMID 31146700, 2019). "Several genes were reported only in syndromic cases; CHD7 (CHARGE syndrome), CR1 (van der Woude syndrome), EFNB1 (craniofrontonasal syndrome), KISS1R (Kallmann syndrome), MID1 (Opitz G/BBB syndrome), REN (van der Woude syndrome), and SOX9 (Pierre-Robin syndrome)." (PMID 31122291, 2019).
CHARGE syndrome (continued). "Our findings further reveal that patients should not be rejected for CHD7 mutational analysis even if they do not fulfill CHARGE syndrome Verloes criteria." (PMID 29945602, 2018). "The incidence of CHARGE syndrome (OMIM 21400) was evaluated at 1 in 10,000–15,000 newborns and about 60–70% of children clinically diagnosed with CHARGE have genetic mutations in the CHD7 gene." (PMID 30317490, 2018). "The function of CHD7 in oligodendrogenesis may help to explain the structural defects in white matter and corpus callosum of CHARGE syndrome patients." (PMID 29033785, 2017). "Dissecting mechanism behind the adult neurogenic defect in Chd7 CKO mice reveals the function of CHD7 in neurodevelopment, which may help us to understand the cognitive deficiency that is frequently observed in CHARGE syndrome patients." (PMID 29033785, 2017). "The introduction of CHARGE syndrome‐associated mutations in the ATP‐dependent chromatin remodeling and chromodomains of CHD7, tested in nucleosome remodeling assays, provided proof that chromatin remodeling activity is central to the pathogenesis of CHARGE syndrome." (PMID 29168327, 2017). "The conditional deletion of chd7 in mice recapitulates most symptoms of CHARGE syndrome." (PMID 28649742, 2017). "Our findings imply a specific function for CHD7 in controlling the spatiotemporal initiation of cerebellar fissures and show that normal fissure formation requires bi‐allelic Chd7 expression, consistent with the haploinsufficient nature of CHARGE syndrome." (PMID 29168327, 2017). "Chd7+/− mice are viable and phenocopy a number of aspects of CHARGE syndrome, including partial penetrance of ventricular septal defects (VSDs) and interrupted aortic arch type B (IAA-B), although the full spectrum and severity of CHARGE cardiovascular malformations are not seen." (PMID 26102480, 2015). "In conclusion, small deletions including the CHD7 gene result in CHARGE syndrome." (PMID 26334530, 2015). "Furthermore, enlarged vestibular aqueduct, incomplete partition type III, lateral canal dysplasia as a manifestation of CHARGE syndrome was a very highly penetrant feature of mutations in SLC26A4, POU3F4, and CHD7, respectively in this population." (PMID 25373420, 2014). "The c.7880G>A (p.R2627Q) mutation identified in CHD7 was not the same mutation, but was found at the same position, as the one detected in a patient with CHARGE syndrome." (PMID 24066114, 2013). "Mutations in the Chromodomain Helicase DNA-binding protein 7 (CHD7) gene are responsible for most cases of Colobomata, Heart defect, Atresia choanae, Retarded growth and development, Genital hypoplasia, Ear anomalies/deafness (CHARGE) syndrome." (PMID 24198816, 2013). "They suggested that CHD7 gene analysis should be performed in KS patients who have at least two of the following features of CHARGE syndrome: ocular coloboma, choanal atresia/stenosis, characteristic external ear anomaly, cranial nerve dysfunction, or balance disturbance." (PMID 24204987, 2013). "Furthermore, knockdown of zebrafish chd7 results in abnormalities similar to those described in CHARGE Syndrome, as we observed inner ear, heart, eye, cranial ganglia, neural crest and skeletal defects in chd7 morphants." (PMID 22363697, 2012). "The relatively mild phenotype of our patient with the truncating mutation Q51X in CHD7 demonstrates that nonsense mutations are not always fully penetrant for CHARGE syndrome." (PMID 22724017, 2012). "Thus, sporadic CHD7 mutations occurred in 6% of IHH/KS patients studied, allowing them to conclude that IHH/KS can represent a milder allelic variant of CHARGE syndrome." (PMID 21995344, 2011).
CHARGE syndrome (continued). "Genetic analysis of the CHD7 gene should be performed in cases with semicircular canal aplasia considering the high mutation rate even when the other typical features of CHARGE syndrome are not present." (PMID 21931733, 2011). "Heterozygous CHD7 (chromodomain helicase DNA-binding protein 7, MIM 608892) mutations have been identified in approximately 60%-70% of patients with clinically diagnosed CHARGE Syndrome and are most commonly due to de novo truncating mutations." (PMID 21995344, 2011). "Chromosomal abnormalities with or without involvement of the CHD7 gene also have been reported to cause phenotypic features of CHARGE syndrome." (PMID 21931733, 2011). "Finally, the CHD7 gene has recently been shown to be involved with the pathogenesis of other diseases, in addition to the CHARGE syndrome." (PMID 20925924, 2010). "Besides CHD7 and CHARGE syndrome, there are few developmental disorders known to result from mutations in ATP dependent remodeling genes." (PMID 20657659, 2010). "Subsequent sequencing of the critical region revealed heterozygous mutations in CHD7, a gene which encodes for a chromodomain helicase DNA-binding protein that is expressed during embryogenesis, in 10 subjects, suggesting that CHD7 haploinsufficiency leads to CHARGE syndrome." (PMID 21532774, 2010). "Therefore, it is assumed that the mechanistic link between the CHARGE syndrome pathogenesis and the CHD7 protein would be its potential role in regulating embryonic development by affecting chromatin structure and gene expression." (PMID 20925924, 2010). "However, no pathogenic variants were identified neither in the coding regions of CHD7, the principal gene implicated in CHARGE syndrome, nor in any other known disease-causing genes." (PMID 40692712, 2025). "Observations show that chd7 mutant zebrafish exhibit decreased heart rates, prolonged anesthesia requirements, and elevated respiratory rates upon awakening from anesthesia, and a study investigated the gene expression of phox2ba and phox2bb in a zebrafish model of CHARGE syndrome." (PMID 38892128, 2024). "This may explain why our patient had only hypogonadism without the more complex phenotype of CHARGE syndrome that is usually associated with more damaging CHD7 mutations." (PMID 39596130, 2024). "Thus, the enhancers identified here represent potential alternative screening sites for CHARGE syndrome individuals without pathogenic variants within the CHD7 gene body." (PMID 39418292, 2024). "Following this discovery, the phenotypic spectrum expanded to phenotypes that do not fulfill the previously proposed CHARGE syndrome clinical diagnostic criteria, with heterozygous [likely] pathogenic variants in CHD7 seeming to cause a wide spectrum of phenotypes, including CHARGE syndrome." (PMID 38790272, 2024). "However, this seems unlikely for CHD7, since large deletions and other variants leading to absent or truncated proteins have been described to result, in general, in a more severe CHARGE syndrome phenotype than missense variants." (PMID 37668839, 2023). "Whereas CHD7 mutations have been identified in some patients with isolated HH without a diagnosis of CHARGE syndrome, it remains unclear whether CHD7 mutations can be identified in patients with CPHD who do not fulfill the criteria for CHARGE syndrome." (PMID 37231428, 2023). "We report a rare case of CPHD harboring CHD7 mutation without CHARGE syndrome." (PMID 37231428, 2023). "We report a case of clinically atypical CHARGE syndrome associated with 7q11.23 duplication and with no identified CHD7 variant in a term baby girl born with small anterior and large posterior retinochoroidal colobomas, hemifacial palsy, atrial septal defect, and external ear abnormalities." (PMID 35246073, 2022). "Moreover, in addition to CHARGE syndrome patients, CHD7 mutations have also been identified in non-syndromic patients with congenital heart defects." (PMID 36568983, 2022).
CHARGE syndrome (continued). "Failure of CHD7 to play its normal role in regulating genes relating to differentiation and motility of neural crest derivatives, including the neural crest component of the periocular mesenchyme, is the likely etiology of the abnormalities seen in CHARGE syndrome." (PMID 35246073, 2022). "However, the pathogenetic mechanisms that connect loss of CHD7 to the ocular complications observed in CHARGE syndrome have not been identified." (PMID 36172288, 2022). "The most common endocrine abnormality in patients with CHARGE syndrome is the disturbance in gonadotropins function ranged from delay puberty to persistent hypogonadotropic hypogonadism with different olfactory phenotypes, resulted by specific role of CHD7 in GnRH neuronal embryogenesis." (PMID 34297504, 2021). "Clinical features may guide the selection of targeted genetic tests, for example cytogenetic tests such as fluorescence in situ hybridization (FISH) or comparative genomic hybridisation (CGH) where there are features of 22q11.2del, CHD7 sequencing for CHARGE syndrome, and FOXN1 for nude SCID." (PMID 33257998, 2021). "Genotype analysis of CHD7 based on ClinVar and CHD7 database demonstrated the mutation spectrum and phenotypes of CHARGE syndrome which might be contributed to the study of CHD7 mutation-associated CHARGE syndrome." (PMID 32625235, 2020). "Interestingly, individuals with CHARGE syndrome and mouse models of CHD7 deficiency show cerebellar hypoplasia but not microcephaly or macrocephaly, and CHD7 promotes granule cell, but not cortical neural progenitor cell, proliferation." (PMID 33060836, 2020). "The first subject was initially assessed for CHARGE syndrome with clinical presentations of autism spectrum disorder together with iris and retinal colobomas, and with a non-coding VUS having been identified in the CHARGE-associated gene, CHD7 (NM_017780.3:c.5534+16T>C)." (PMID 31029150, 2019). "Although hydrocephalus has rarely been reported in conjunction with pathogenic CHD7 variants, it was believed that the isolated ventriculomegaly could not be unequivocally attributed to the CHD7 variant in the absence of any other features of CHARGE syndrome." (PMID 30712880, 2019). "Interestingly, three of our patients with CHD7 mutations had minor CHARGE features, namely hearing deficit, renal anomalies and intellectual disability, respectively, but insufficient for a clinical diagnosis of CHARGE syndrome." (PMID 30733481, 2019). "Therefore, molecular testing of KMT2D should be considered in patients clinically diagnosed with CHARGE syndrome without CHD7 mutations." (PMID 29321794, 2017). "Moreover, Chd7-deficient Xenopus embryos have reduced semaphorin-3a (sema3a) expression suggesting that disturbed sema3a signaling contributes to the pathogenesis of the CHARGE-related disorder Kallmann syndrome and possibly CHARGE syndrome itself." (PMID 29367567, 2016). "Interestingly, CHD8 interacts with CHD7 and the majority of CHARGE syndrome patients suffer from ASD, demonstrating that mutations in related epigenetic pathways can result in different syndromes with shared symptoms depending on the context and nature of a particular mutation." (PMID 26188466, 2016). "However, the role of CHD7 in generating the array of congenital anomalies seen in individuals with CHARGE syndrome remains unclear." (PMID 26935104, 2016). "Mutations or polymorphisms in these genes could conceivably be responsible for much of the clinical variation that is so typical of CHARGE syndrome by altering the penetrance and/or expressivity of specific disease traits in the context of CHD7 haploinsufficiency." (PMID 26411921, 2015).
CHARGE syndrome (continued). "In the remaining 5–10% of patients with clinically typical CHARGE syndrome, the apparent lack of CHD7 mutations may be explained by alterations in CHD7 that are not detected with routine genotyping strategies." (PMID 26411921, 2015). "What about Patients with CHARGE Syndrome without CHD7 Mutations?" (PMID 26411921, 2015). "Given that the zebrafish chd7 gene is highly similar to the human CHD7 gene, elucidating roles for Chd7 in zebrafish development could significantly contribute to our understanding of the function of Chd7 in CHARGE syndrome pathogenesis." (PMID 22363697, 2012). "From the overlapping expression pattern between Chd7 and Fam124B at murine embryonic day E12.5 and the high expression of Fam124B in the developing mouse brain, we conclude that Fam124B is a novel protein possibly involved in the pathogenesis of CHARGE syndrome and neurodevelopmental disorders." (PMID 23285124, 2012). "In conclusion, 8 mutations of the CHD7 gene including 5 novel mutations were identified in Korean patients with CHARGE syndrome showing semicircular canal aplasia and profound hearing loss, which will broaden the genotypic and phenotypic spectrum of CHARGE syndrome." (PMID 21931733, 2011). "In summary, we report an 18 year old male with CHARGE syndrome and a unique phenotype, including primary hypoparathyroidism, bilateral MCDK, a limb anomaly, disrupted testicular growth, and an atypical eyelid coloboma, who harbored a heterozygous G744S CHD7 mutation." (PMID 21995344, 2011). "The patient who carried a missense mutation of the CHD7 gene presented with the mildest symptoms demonstrating only mild developmental delay and mental retardation without any classical features of CHARGE syndrome other than hearing loss and semicircular canal aplasia." (PMID 21931733, 2011). "The CHD7 gene was not mutated in one patient diagnosed as typical CHARGE syndrome." (PMID 21931733, 2011). "As a first step to investigate the function of CHD7, we used the technique of chromatin immunoprecipitation followed by massively parallel DNA sequencing (ChIP-Seq) to map CHD7 sites in mouse ES cells, representing the earliest precursor to all tissues affected in CHARGE syndrome." (PMID 20657823, 2010). "How might haploinsufficiency of CHD7 give rise to CHARGE syndrome?" (PMID 20657823, 2010). "The WGS data analysis confirmed the absence of intragenic or structural variants involving CHD7 and excluded the occurrence of other clinically relevant variants in genes previously reported to be implicated in neurodevelopmental disorders with features overlapping with CHARGE syndrome." (PMID 40004505, 2025). "Therefore, the term ‘CHD7 disorder’ has been adopted more recently, referring to the entire phenotypic spectrum that can be associated with heterozygous CHD7 pathogenic variants and is not equivalent to a diagnosis of CHARGE syndrome." (PMID 38790272, 2024). "However, it remains unclear whether CHD7 mutations can be detected in patients with CPHD who do not fulfill the criteria for CHARGE syndrome." (PMID 37231428, 2023). "chd7 mutant fish are a valuable preclinical model to investigate anesthesia in CHARGE syndrome and reveal a novel functional link between CHARGE syndrome and CCHS." (PMID 37239446, 2023). "The phenotypic similarity between the CHARGE syndrome and the CDK9-related disorder is currently unexplainable by molecular interaction between CHD7 and CDK9." (PMID 33640901, 2021). "Thus, understanding CHD7 function in the regulation of the epigenome in granule cells of the cerebellum may advance our understanding of both chromatin remodeling in the brain as well as the pathogenesis of CHARGE syndrome." (PMID 34588434, 2021). "Moreover, there is no CHARGE syndrome patient who is figured out to have CHD7 homozygous mutations." (PMID 34616726, 2021). "Our results suggest that the alteration induces the premature truncation of the CHD7 protein (UniProtKB: Q9P2D1), thus resulting in CHARGE syndrome." (PMID 31315586, 2019).